IRF9 (interferon regulatory factor 9)
Description:
Transcription factor that plays an essential role in anti-viral immunity. It mediates signaling by type I IFNs (IFN-alpha and IFN-beta). Following type I IFN binding to cell surface receptors, Jak kinases (TYK2 and JAK1) are activated, leading to tyrosine phosphorylation of STAT1 and STAT2. IRF9/ISGF3G associates with the phosphorylated STAT1:STAT2 dimer to form a complex termed ISGF3 transcription factor, that enters the nucleus. ISGF3 binds to the IFN stimulated response element (ISRE) to activate the transcription of interferon stimulated genes, which drive the cell in an antiviral state.
Synonyms: IRF-9; ISGF3G; ISGF3; p48
Tractability: PROTAC: UniProt records ubiquitination sites on it; ubiquitination databases record sites on it; its protein half-life has been measured.
Gene: Protein-coding gene on chromosome 14 (24,161,101 to 24,168,043, forward strand). Ensembl gene ENSG00000213928.
Subcellular location: Cytoplasm; Nucleus
Subcellular location (Human Protein Atlas): Cytosol
Pathways (Reactome):
Immune System: Interferon alpha/beta signaling; Interferon gamma signaling
Gene Ontology:
Molecular function: protein binding; RNA polymerase II cis-regulatory region sequence-specific DNA binding; sequence-specific double-stranded DNA binding; DNA-binding transcription factor activity; DNA-binding transcription factor activity, RNA polymerase II-specific; transcription cis-regulatory region binding
Biological process: positive regulation of transcription by RNA polymerase II; cell surface receptor signaling pathway; immune system process; regulation of transcription by RNA polymerase II; transcription by RNA polymerase II; regulation of DNA-templated transcription
Cellular component: cytosol; ISGF3 complex; nucleus; chromatin; cytoplasm; nucleoplasm
Genetic constraint (gnomAD): Loss-of-function variants: 15 observed, 46.28 expected, observed/expected ratio (o/e) 0.32, 90% interval 0.22 to 0.5. The upper end of that interval is the gene's LOEUF score, 0.5, which puts it in group 2 of 6, group 1 being the genes least tolerant of losing a copy. Missense variants: 372 observed, 510.77 expected, observed/expected ratio (o/e) 0.73, 90% interval 0.67 to 0.79. Synonymous variants: 187 observed, 195.05 expected, observed/expected ratio (o/e) 0.96, 90% interval 0.85 to 1.08.
Gene-disease validity (ClinGen):
ClinGen rates the evidence that IRF9 causes each of these diseases.
immunodeficiency 65, susceptibility to viral infections (autosomal recessive): Moderate.
Homologues: Orthologues: chimpanzee IRF9 (94% identical), macaque IRF9 (83% identical), pig IRF9 (81% identical), rat Irf9 (72% identical), mouse Irf9 (70% identical), guinea pig IRF9 (66% identical), zebrafish irf9 (35% identical), zebrafish irf4b (31% identical). Paralogues in human: IRF4 (32% identical), IRF8 (32% identical), IRF5 (27% identical), IRF6 (25% identical), IRF7 (22% identical), IRF3 (20% identical), IRF1 (15% identical), IRF2 (15% identical).
Diseases named in the same sentence as IRF9 in open-access papers:
IRF9 is named in the same sentence as 132 diseases in open-access papers, as found by Europe PMC text mining. Sharing a sentence is not in itself a finding about the gene and the disease. The quoted sentences say what the papers report.
viral infection (57 papers, 2013 to 2026). "In humans, it was found that mutations in IRF9 resulted in increased susceptibility to viral infection and that IRF9 deficient cells were unable to induce multiple interferon-stimulated genes (ISGs)." (PMID 40315186, 2025). "Humans with mutations in IRF9 have the immunologic disorder Immunodeficiencey-65, and are susceptible to viral infections." (PMID 38275965, 2024). "Specifically, the inherited IRF9 deficiency is related to a life-threatening influenza pneumonitis in early infancy and impaired control of multiple viral infections." (PMID 36357830, 2022). "IRF9 deficiency has been reported to increase susceptibility to several forms of viral infections and result in decreased levels of MX-1 and ISG-1541." (PMID 36273032, 2022). "Most of these DEGs were associated with the host response to virus infection and type I interferons, while others such as IRF9, PML, IRF7, STAT1 and IFIH1 were related to interferon signaling." (PMID 33301474, 2020). "IRF9 expression has been associated with better outcomes in viral infections, including COVID-19." (PMID 39590591, 2024). "IRF9 deficiency was associated with impaired control of other viral diseases and may act as a risk biomarker of COVID-19." (PMID 38731851, 2024). "Various irfs (e.g., irf1, irf2, irf3, irf4b, irf7, irf9, and irf10) were previously found upregulated with poly(I:C) or viral infection in teleost species." (PMID 39211041, 2024). "Interferon regulatory factor 9 (irf9) activates the type I interferon response during viral infection, and this was upregulated with mVenus-PR8 infection." (PMID 38275965, 2024). "Among IRFs, IRF9-deficient mice exhibit especially severely impaired production of IFN-α and IFN-β induced by viral infection and enhanced susceptibility to infection with encephalomyocarditis virus." (PMID 39596618, 2024). "ITGAM, RUNX1, and PSTPIP2 formed one cluster with high expression in subjects with confirmed bacterial infections, whereas LY6E and IRF-9 formed another cluster with high expression, mainly in patients with confirmed viral infections." (PMID 36900096, 2023). "ITGAM, RUNX1, and PSTPIP2 formed one cluster with high expression in subjects with confirmed bacterial infections, whereas LY6E and IRF-9 formed another cluster with high expression in patients with confirmed viral infections." (PMID 36900096, 2023). "Upon activation of ifn receptors by ligands, STAT1 and STAT2 are phosphorylated and form ISGF3 complex with IRF9, which is shuttled into the cell nucleus to trigger the expression of ISGs involved in immune response against viral infection." (PMID 35392096, 2022). "The MERS-CoV-shared genes KRT6B and TNFAIP3 had a high p-value associated with SARS-CoV-2, whereas genes such as OAS1-3, IRF9, IRF7, STAT1, PML and IFIH1 were highly associated with host responses to viral infections and type I interferon." (PMID 33301474, 2020). "Under these conditions, unphosphorylated (U-)ISGF3, but also U-STAT1 and U-STAT2/IRF9 are proposed to mediate constitutive IFN-independent expression of ISGs to protect against viral infection [reviewed in]." (PMID 31178872, 2019). "Phosphorylated STAT1 and STAT2 then bind with IRF9 to form a complex called IFN-stimulated gene factor 3 (ISGF3) to initiate the transcription of hundreds of genes that act to block viral infection." (PMID 30840887, 2019). "The potency of ISGs against viral infections is highlighted by the many ways viruses have evolved to interfere with IRF9, alone or as part of ISGF3." (PMID 30147694, 2018). "Transfection of the IRF9-S2C plasmid for 4 h induced a modest 2-fold induction in luciferase activity and this was increased further by virus infection." (PMID 27907166, 2016).
viral infection (continued). "IRF3 and IRF7 have been implicated as positive regulators of IFN-I gene expression induced by virus infections, whereas IRF9 constitutes an IFN-stimulated gene factor 3 together with STAT1 and STAT2, and is responsible for the induction of the IRF7 gene." (PMID 24903089, 2014). "We also assessed the role of IRF9 in protection against virus infection." (PMID 40597257, 2025). "However, upon virus infection, STATs are activated via phosphorylation by JAKs and bind interferon regulatory factor 9 (IRF9) to form the IFN-stimulated gene factor 3 (ISGF3) complex." (PMID 39861822, 2024). "Since pI215L is an essential viral protein for ASFV replication, we could not generate a defective viral mutant lacking the entire I215L gene to further assess the role of pI215L in IRF9 degradation in the context of viral infection." (PMID 35972295, 2022). "IRF9 expression levels have been considered as an important determinant of viral disease severity." (PMID 33936086, 2021). "The significant downregulation of interferon signature genes, such as Adar (DRADA), Ddx58 (RIG-I), Ddx60 (DDX60), Stat1 (STAT1), Ifih1 (MDA5), Trim25 (TRIM25), Irf7 (IRF7), and Irf9 (IRF9) in infected Cd47−/− NK cells is consistent with the impaired Cd47−/− NK cell response to viral infection." (PMID 30643501, 2018). "Interestingly, chickens are lacking essential components of innate immune system (e.g., RIG-I, IRF3, IRF9); they yet mount profound innate immune responses against virus infections." (PMID 30271403, 2018). "In addition, it is conceivable that IRF9-inhibition by the immediate early gene ORF63 precedes STAT2 inhibition due to sequential expression of the respective inhibitory proteins during viral infection." (PMID 25973608, 2015). "In conclusion, the relevance of OAS1, IRF9, and IFI6 in controlling the viral infection was confirmed." (PMID 38731851, 2024). "Downstream IFN-related factor IRF9 is also a necessary component of the ISG activation complex, and the absence of IRF9 leads to the blockade of ISG activation after viral infection." (PMID 34372578, 2021). "Collectively, these findings show that human IRF9- and ISGF3-dependent type I and III IFN responsive pathways are essential for controlling viral infections, including IAV." (PMID 31574965, 2019). "The interferon regulatory factor 9 (IRF9) promotes negative feedback in the interferon response, and its deficiency causes excessive inflammation in viral infections." (PMID 39590591, 2024). "IRF1 and IRF9 are induced by both IFN-I and -II and viral infection." (PMID 29892288, 2018). "Irf9 transcripts were not affected by virus infection in microglia but increased modestly in astrocytes." (PMID 29491163, 2018). "Mutations affecting IRF family members IRF1, IRF3, IRF7, IRF8, or IRF9 have been described in patients presenting with inborn errors of immunity (IEI) highlighting the importance of these factors for the cellular host defense against mycobacterial and/or viral infections." (PMID 37809068, 2023). "Apart from this similarity, different virus infection pathways owned their unique genes, with STAT1,RSAD2 and IRF9 in the influenza A pathway,IL-2RA,IL-2RB and CD40 in the HTLV-1 infection pathway, HCFC1, MAP3K7, SOCS3, IRF9, HMGN1, and FAS in the herpes simplex infection pathway." (PMID 35795668, 2022).
COVID-19 (26 papers, 2020 to 2026). A disease caused by infection with severe acute respiratory syndrome coronavirus 2. "We describe an unvaccinated child at risk for life-threatening COVID-19 due to an inherited deficiency of IRF9, which governs ISGF-3–dependent responses to type I and III interferons (IFN)." (PMID 34702736, 2021). "Among these proteins, OAS1 and IRF9 have been reported as potential biomarkers for COVID-19 prognosis." (PMID 38731851, 2024). "A recent study have demonstrated that IRF9 among many other pro-inflammatory genes hold a high significance during immune related COVID-19 response." (PMID 33936086, 2021). "As for IRF9, according to COVID-19-related studies, similar with LGALS3BP, this gene is typically expressed in multiple respiratory infection diseases." (PMID 33505977, 2020). "IRF7 (interferon regulatory factor 7) can mediate inflammatory responses, and a lack of IRF9 results in increased COVID-19 risk." (PMID 40877796, 2025). "Furthermore, STAT1 (21,435th → 32nd), STAT2, EGFR, and IRF9 (2455th → 36th) are involved in interferon signaling and have been suggested in numerous COVID-19 studies." (PMID 36291657, 2022). "Our in-depth phenograph-guided analysis of the neutrophil compartment revealed the enrichment of activated neutrophil immunotypes in moderate COVID-19 patients, associated with higher circulating levels of molecules involved in the IFN-mediated antiviral response (i.e., IRF9, IL-12b, IFNɣ)." (PMID 34548411, 2021). "Our results showed a higher expression in COVID-19 cases, that included only asymptomatic or mild forms of the disease, then, the higher expression of IRF9 may be related to better outcomes which is in accordance to other studies which found IRF9 deficient levels in severe cases." (PMID 37389217, 2023). "Based on relevant results reported in the existing literature and a previous study of our group, the genes CCL5, OAS1, IRF9, IFI6, TGFB1, IL1B, and TFRC were analyzed in the present study in relation to the severity of COVID-19." (PMID 38731851, 2024). "In the present study, the differential expression of seven genes related to immunity, IRF9, CCL5, IFI6, TGFB1, IL1B, OAS1, and TFRC, was analyzed in individuals with COVID-19 diagnoses of different disease severities." (PMID 38731851, 2024). "A previous study found that seriously affected COVID-19 patients had an increased level of STAT1 and IRF9." (PMID 37053191, 2023). "While a protective effect of OAS1, IRF9, and IFI6 in asymptomatic and mild COVID-19 is confirmed, the role of TGFB1 and CCL5 is still controversial." (PMID 37389217, 2023). "The following four genes were enriched in the related pathways of coronavirus disease (COVID-19) from KEGG database: FCGR2A (FcRII–A), IRF9, OAS1(2′-5′-oligoadenylate synthetase 1) and CYBB (NOX2)." (PMID 36555339, 2022). "Four genes: FCGR2A (FcRII–A), IRF9, OAS1 (2′–5′-oligoadenylate synthetase 1) and CYBB (also known as NOX2) were highlighted in the related pathways of coronavirus disease (COVID-19) from KEGG database." (PMID 36555339, 2022). "IRF9 was diminished among COVID-19 WHO 6–8 participants and control WHO 7–8 participants compared to healthy donors and participants with mild or moderate COVID-19." (PMID 34352228, 2021). "In this study, the relative expression of IRF9, CCL5, IFI6, TGFB1, IL1B, OAS1, and TFRC genes (related to immunity and antiviral activity) was analyzed in upper airway samples from 127 individuals (97 COVID-19 positive and 30 controls) by using a two-step RT-PCR." (PMID 37389217, 2023). "Intriguingly, despite the absence of autoantibodies directed at type I interferons, nearly all participants who developed severe COVID-19 failed to induce STAT1, STAT2, IRF1, and IRF9 expression (among other IFN-stimulated genes)." (PMID 34352228, 2021). "TF activity analysis indicated a robust regulation by IRF2/IRF9 and STAT1/2 for this cluster of cells, within both severe and non-severe COVID-19." (PMID 34721400, 2021).
breast carcinoma (11 papers, 2015 to 2025). "For instance, IRF9 has been reported as a promising therapeutic and biomarker target for skin malignancy and breast cancer." (PMID 40088196, 2025). "In breast cancer, however, the suppression of IRF9 or STAT2 transcription induces resistance to the PARP inhibitor." (PMID 39062738, 2024). "We revealed that the loss of IRF9 leads to increased resistance to the PARP inhibitor in MDA-MB-468 cells, and a similar desensitization was observed in another breast cancer cell line, MDA-MB-231." (PMID 39062738, 2024). "Our study identified IRF9 via a CRISPR screen aimed at identifying regulators of PARP inhibitor sensitivity in breast cancer." (PMID 39062738, 2024). "We expanded this to a larger independent TNBC-specific cohort of 159 patients and confirmed expression of IRF9 as a predictor of prolonged breast cancer-specific survival." (PMID 31482136, 2019). "To assess this, we used a panel of human breast cancer cell lines and as with our observed expression in primary tumor tissues, the expression of IRF9 and IRF7 was heterogeneous across cell lines and subtypes." (PMID 31482136, 2019). "Further, upregulation of ISGs like STAT1, STAT2, or IRF9 is known to promote cancer resistance to chemotherapy and radiotherapy as demonstrated in human head and neck squamous cell carcinoma and breast cancer." (PMID 27533247, 2016). "However, IRF9 has been shown to confer chemoresistance in breast cancer, and suggested as a prognostic marker for chemotherapy and overall survival in triple-negative breast cancer (TNBC), in which high IRF9 levels are associated with a better outcome." (PMID 33430083, 2021). "In order to independently validate IRF9 as a prognostic marker, we analyzed baseline IRF9 expression in an adjuvant cohort of 414 breast cancer patients of mixed breast cancer subtypes (ER± luminal A and B, HER2+, and TNBC) where chemotherapy was administered subsequent to tumor resection." (PMID 31482136, 2019). "There was also a clear trend between high IRF9 expression and a decreased risk of local relapse and breast cancer-specific death, yet this was not significant, likely due to the size of this cohort." (PMID 31482136, 2019). "In the present study, STAT1/IRF9 expression in breast cancer samples was analysed." (PMID 30334368, 2018). "In this study, we conducted a CRISPR-dCas9 interference screen in a BRCA1/2-proficient breast cancer cell line to identify genes that modulate the cell response to the PARP inhibitor olaparib and identified IRF9 as a candidate." (PMID 39062738, 2024). "Based on these findings, it should not be generalized that IRF9 is beneficial in all patients with breast cancer." (PMID 33430083, 2021). "Initially, we evaluated the expression of IFN-signaling proteins (STAT1 (Y701), STAT1, STAT2, IRF9) and IFN-stimulated proteins that induce an antiviral state (OAS1 and MxA) in MCF7/pS, MCF7/pR, 231/pS and 231/pR breast cancer cells in the absence or presence of palbociclib." (PMID 31100952, 2019). "In the breast cancer cell line MCF7, which does not originate from TNBC and was still able to respond to IFN treatment with reduced proliferation, the overexpression of IRF9, but not STAT1 or STAT2, increased the resistance of cells against the chemotherapeutic drug paclitaxel." (PMID 33430083, 2021).